LINC01614 (long independently transcribed non-coding RNA 1614)
Synonyms: LCAL4; TCONS_00003105
Gene: Long non-coding RNA gene on chromosome 2 (215,713,623 to 215,720,947, forward strand). Ensembl gene ENSG00000230838.
Diseases named in the same sentence as LINC01614 in open-access papers:
LINC01614 is named in the same sentence as 19 diseases in open-access papers, as found by Europe PMC text mining. Sharing a sentence is not in itself a finding about the gene and the disease. The quoted sentences say what the papers report.
breast carcinoma (11 papers, 2019 to 2024). "Five ARLs (MAPT.IT1, AL133467.1, AC004585.1, AC055854.1, and LINC02613) were identified as protective factors, whereas two (LINC01614 and C6orf99) were identified as risk factors for breast cancer." (PMID 38189818, 2024). "A total of 105 paired primary breast cancer and adjacent normal tissues were used for analysis, and LINC01614, VCAN-AS1 and LINC00478 were found to be differentially expressed." (PMID 36782197, 2023). "In esophageal squamous cell carcinoma and breast cancer, LINC01614 was also suggested as a survival predictor and had an impact on tumor invasion." (PMID 34604079, 2021). "Elevated expression of LINC01614 was subsequently validated in primary breast cancer tissue and breast cancer cell lines." (PMID 31263577, 2019). "Collectively, LINC01614/miR-204-5p/SLC31A1 might be a potential axis related to cuproptosis in breast cancer." (PMID 37884650, 2023). "Moreover, LINC01614 was found to regulate epithelial-mesenchymal transition and tamoxifen sensitivity in luminal breast cancer cells." (PMID 37884650, 2023). "Linc01614, speculated as a biomarker for poor prognosis in breast cancer, is significantly upregulated in various tumor tissues and highly correlated with TGF-β signaling and ECM remodeling." (PMID 37504302, 2023). "However, LINC01614 has been reported as an oncogene and biomarker in several cancers, including gastric cancer, esophageal squamous cell carcinoma, breast cancer, and LUAD." (PMID 36209111, 2022). "LINC01614 was relevant to the HR+/HER2 + breast cancer molecular subtype and accelerated breast cancer cell proliferation and migration by TGF-β and focal adhesion kinase (FAK) signaling." (PMID 38655053, 2024). "The results demonstrated that breast cancer patients with increased levels of AC009686.2, AC132807.2, AC093515.1, AC129926.2, AL513123.1, RHPN1-AS1, KCNMB2-AS1, LINC01614, LINC01705, and C6orf99 had a better overall survival." (PMID 37884650, 2023). "Further, LINC01614, RP11‐490M8.1, and CTB‐92J24.3 were novel DElncRNAs identified in early‐stage breast cancer." (PMID 30959550, 2019).
lung adenocarcinoma (8 papers, 2018 to 2025). A carcinoma that arises from the lung and is characterized by the presence of malignant glandular epithelial cells. "We tried to identify the function of LINC01614 in lung adenocarcinoma (LUAD) and reveal its underlying mechanisms." (PMID 29934982, 2018). "For instance, in lung adenocarcinoma, LINC01614 promotes cell proliferation and suppresses apoptosis, highlighting its role in enhancing tumour growth and survival." (PMID 40735832, 2025). "The transfer and functional role of LINC01614 in lung adenocarcinoma (LUAD) and CAFs were investigated using 4-thiouracil-labeled RNA transfer and gain- and loss-of-function approaches." (PMID 36209111, 2022). "LINC01614 also promotes the carcinogenesis of lung adenocarcinoma by downregulating expression of microRNA-217 and upregulating expression of Forkhead Box Protein P1 (FOXP1)." (PMID 33362844, 2020). "Similarly, upregulation of LINC01614 has been proposed as a prognostic indicator of survival in non-small cell lung cancer (NSCLC), and LINC01614 knockdown inhibits lung adenocarcinoma progression." (PMID 39282156, 2023). "Knockdown of LINC01614 inhibits lung adenocarcinoma cell progression." (PMID 32190687, 2020). "Furthermore, we found that LINC01614 was significantly upregulated in both lung adenocarcinoma tissues and lung squamous cell carcinoma tissues, with an average increased fold of 3.72 and 2.95 respectively." (PMID 31348244, 2019).
gastric cancer (5 papers, 2021 to 2022). A primary or metastatic malignant neoplasm involving the stomach. "LINC01614 is identified as an oncogenic lncRNA that promotes proliferation and migration in gastric cancer." (PMID 35047016, 2021). "Silence of CCDC144NL-AS1 and LINC01614 both significantly suppressed the cell proliferation and migration of gastric cancer cells, and also promoted the chemosensitivity of gastric cancer cells to 5-fluorouracil." (PMID 35083139, 2021). "The survival analysis showed that high expression of CCDC144NL antisense RNA 1 (CCDC144NL-AS1) and LINC01614 was positively correlated with the poor prognosis of patients with gastric cancer." (PMID 35083139, 2021). "The qPCR assay was performed to confirm the expression of CCDC144NL-AS1 and LINC01614 in gastric cancer cells, and CCDC144NL-AS1 and LINC01614 were significantly up-regulated in AGS and SGC7901 cells compared to that in GES-1 cells." (PMID 35083139, 2021). "The in vitro validation results showed that CCDC144NL-AS1 and LINC01614 were both up-regulated in the gastric cancer cells." (PMID 35083139, 2021). "Silence of CCDC144NL-AS1 and LINC01614 both significantly suppressed the cell proliferation and migration of gastric cancer cells, and also promoted the chemosensitivity of gastric cancer cells to cisplatin." (PMID 35083139, 2021). "Through analyzing the dataset GSE95667 in GEO database, it is found that the expression of LINC01614 in gastric cancer tissues is also upregulated with the log2FC of 1.953 (p < 0.05)." (PMID 34691143, 2021). "For instance, LINC01614, which was reported to suppress the malignant phenotypes of gastric cancer cells, could also regulate lung cancer cell proliferation and migration." (PMID 35818395, 2022). "In conclusion, our study performed the WGCNA and revealed that CCDC144NL-AS1 and LINC01614 might be potential biomarkers for the prognosis of gastric cancer patients." (PMID 35083139, 2021). "Collectively, our results suggested that the newly identified two lncRNAs (CCDC144NL-AS1 and LINC01614) may act as oncogenes in gastric cancer." (PMID 35083139, 2021). "Our in vitro studies showed that silence of LINC01614 attenuated the progression of gastric cancer cells and enhanced the chemosensitivity of gastric cancer cells to cisplatin, suggesting that LINC01614 may serve as an oncogenic RNA in gastric cancer." (PMID 35083139, 2021). "Further in vitro functional studies indicated that CCDC144NL-AS1 and LINC01614 might serve as oncogenic lncRNAs in gastric cancer." (PMID 35083139, 2021). "We then examined the function of LINC01614 in GC cells in vitro, the results revealed that LINC01614 stimulated the development of gastric cancer, it promotes cell proliferation and colony formation." (PMID 34691143, 2021).
glioma (5 papers, 2021 to 2025). A benign or malignant brain and spinal cord tumor that arises from glial cells (astrocytes, oligodendrocytes, ependymal cells). "In glioma, the upregulation of LINC01614 by SP1 promoted cancer progression by regulating the miR-383/ADAM12 axis." (PMID 38655053, 2024). "Another study reported that, through the regulation of ADAM12, SP1-mediated upregulation of lncRNA LINC01614 functions as a ceRNA for miR-383, thereby facilitating glioma progression." (PMID 33889541, 2021). "Additionally, recent studies have shown that SP1 can induce the expression of LINC01614, thereby enhancing the malignant development of gliomas through the miR‐383/ADAM12 pathway." (PMID 40735832, 2025).
osteosarcoma (5 papers, 2021 to 2024). A usually aggressive malignant bone-forming mesenchymal neoplasm, predominantly affecting adolescents and young adults. "In osteosarcoma, LINC01614 accelerated SNX3 expression by binding miR-520a-3p, further leading to cancer progression." (PMID 38655053, 2024). "In osteosarcoma, LINC01614 as a ceRNA promoted tumor progression through the miR-520a-3p/SNX3 axis." (PMID 38655053, 2024). "Through the miR-520a-3p/SNX3 axis, LINC01614 accelerates the progression of osteosarcoma." (PMID 36843602, 2023). "In a related study, LINC01614 was significantly upregulated in osteosarcoma and could facilitate tumor progression through the miR-520a-3p/SNX3 axis." (PMID 36457749, 2022).
esophageal squamous cell carcinoma (4 papers, 2020 to 2024). Esophageal squamous cell carcinoma (ESCC) is a type of esophageal carcinoma (EC) that can affect any part of the esophagus, but is usually located in the upper or middle third. "Knockdown of LINC01614 inhibited cell growth, migration, and invasion of THCA and esophageal squamous cell carcinoma." (PMID 38655053, 2024).
lung carcinoma (4 papers, 2021 to 2022). "Recent studies have shown that LINC01614 is implicated in lung cancer and oesophageal squamous cell carcinoma, and our study further revealed the oncogenic functions of LINC01614 in GC and suggested potentials of LINC01614 as a biomarker of GC." (PMID 33742127, 2021).
head and neck squamous cell carcinoma (3 papers, 2023 to 2024). A squamous cell carcinoma that arises from any of the following anatomic sites: lip and oral cavity, nasal cavity, paranasal sinuses, pharynx, larynx, and salivary glands. "According to the analysis, LINC01614 is typically overexpressed in most cancers, including head and neck squamous cell carcinoma (HNSC)." (PMID 39596660, 2024). "LINC01614 promotes head and neck squamous cell carcinoma progression via the PI3K/AKT signaling pathway, and miR-616-3p can inhibit cancer progression by downregulating LINC01614 expression." (PMID 37685841, 2023).
pancreatic cancer (2 papers, 2023 to 2025). "According to existing literature, LINC01614 can promote pancreatic cancer progression by WNT/β‐catenin signaling which is the crucial pathway in aortic valve calcification." (PMID 37369992, 2023). "Similarly, in pancreatic cancer, LINC01614 knockdown has been shown to suppress cell processes and inhibit tumour proliferation, further supporting its oncogenic function." (PMID 40735832, 2025).
astrocytoma (1 paper, 2025). "Our findings provide novel insights into the molecular mechanisms underlying astrocytoma progression and highlight the potential of LINC01614 as a therapeutic target." (PMID 40735832, 2025). "By sequestering miR‐128, LINC01614 contributes to the dysregulation of this pathway, promoting astrocytoma progression." (PMID 40735832, 2025). "In this study, we investigated the functional role of LINC01614 in astrocytoma and its interaction with miR‐128, a known regulator of the RAS/Map kinase signalling pathway." (PMID 40735832, 2025). "The identification of LINC01614 as an upregulated lncRNA in astrocytoma opens up new avenues for research aimed at unravelling its functional significance and therapeutic potential." (PMID 40735832, 2025). "LINC01614, a long noncoding RNA, has recently emerged as a potential therapeutic target in the progression of astrocytoma, a type of brain tumour." (PMID 40735832, 2025). "Overall, our study provides valuable insights into the functional role of LINC01614 in astrocytoma progression and its interaction with miR‐128." (PMID 40735832, 2025). "By sponging miR‐128 and subsequently dysregulating the RAS/MAPK signalling pathway, LINC01614 emerges as a key player in astrocytoma progression and a promising therapeutic target." (PMID 40735832, 2025). "In conclusion, LINC01614 has emerged as a potential therapeutic target in astrocytoma progression by sponging miR‐128 to dysregulate the RAS/MAPK signalling pathway." (PMID 40735832, 2025). "Through in vitro experimental assays, we demonstrated that LINC01614 upregulation promotes astrocytoma cell proliferation and invasion, potentially through the sponging of miR‐128." (PMID 40735832, 2025). "LINC01614 is a lncRNA that has been found to be upregulated in astrocytoma, suggesting its potential role in tumour progression." (PMID 40735832, 2025). "One of the key mechanisms through which LINC01614 exerts its influence in astrocytoma progression is by sponging miR‐128." (PMID 40735832, 2025). "Understanding the molecular mechanisms by which LINC01614 contributes to astrocytoma progression could provide valuable insights into the underlying biology of these tumours." (PMID 40735832, 2025). "This upregulation suggests that LINC01614 may play a role in promoting the growth and spread of astrocytoma cells, making it a promising candidate for further investigation as a therapeutic target." (PMID 40735832, 2025). "Targeting LINC01614 or modulating miR‐128 expression may offer new therapeutic strategies for astrocytoma treatment." (PMID 40735832, 2025). "However, the oncogenic role of LINC01614 is not restricted to astrocytoma, as it has been implicated in multiple cancers through interactions with distinct miRNAs and regulatory pathways." (PMID 40735832, 2025).
bladder cancer (1 paper, 2022). "In addition, the overexpression of LINC01614 in bladder cancer could promote tumor proliferation, migration, and invasion through the miR-217/RUNX2 and Wnt/β-Catenin pathway." (PMID 36457749, 2022).
brain tumour (1 paper, 2025). "Targeting LINC01614 and its downstream effectors holds great promise for improving the management of this aggressive form of brain tumour and may pave the way for personalised and targeted treatment approaches in the future." (PMID 40735832, 2025).
breast tumor (1 paper, 2024). "C60rf99, LINC01614, AC004585, MAPT-IT1, and AC004585.1 exhibited significantly higher expression levels in breast tumor tissues than in paired or unpaired normal breast tissues (P < 0.05)." (PMID 38189818, 2024).
lymph node metastasis (1 paper, 2022). "High LINC01614 expression in LUAD tissues was correlated with histological staging and lymph node metastasis." (PMID 36209111, 2022).
malignant glioma (1 paper, 2021). A grade III or grade IV glioma arising from the central nervous system. "Upregulation of LINC01614, induced by SP1, promotes malignant glioma progression by modulating the miR-383/ADAM12 axis." (PMID 35047016, 2021).
tumor (19 papers, 2018 to 2025). "LINC01614 has been identified as one such potential target due to its involvement in the regulation of key signalling pathways implicated in tumour progression." (PMID 40735832, 2025). "LINC01614 was also associated with immune cell infiltration, tumor heterogeneity, cancer stemness, RNA methylation modification, and drug resistance." (PMID 38655053, 2024). "Consistently, an in vivo LINC01614 deficiency model exhibited slow tumor growth rate." (PMID 39282156, 2023). "Conversely, LINC01614 knockdown resulted in cell cycle arrest, potentially hindering tumour cell proliferation." (PMID 40735832, 2025). "Correlation analysis of LINC01614 and tumor stage illustrated that LINC01614 expression was significantly correlated with the tumor stage of 12 human tumors." (PMID 38655053, 2024). "The findings revealed that LINC01614 downregulation significantly inhibited tumor development, relative to that of the control." (PMID 39596660, 2024). "The correlation analysis of molecular subtypes revealed significant differences in LINC01614 expression among seven distinct tumor subtypes." (PMID 38655053, 2024). "To examine how LINC01614 affects tumor growth in vivo, we established a tumor xenograft model in nude mice." (PMID 39282156, 2023). "More importantly, 37 of 78 (47.4%) LUAD patients with abundant CAF infiltration exhibited enhanced hybridization signals of LINC01614 in the tumor cells." (PMID 36209111, 2022). "Consistently, LINC01614 was abundant in CAFs, and LINC01614 expression of tumor cells was positively correlated with the density of α-SMA+ CAFs and the expression of SLC38A2 and SLC7A5 in tumors." (PMID 36209111, 2022). "We found that LINC01614 is significantly overexpressed in PTC compared with the non-tumor thyroid tissues in both TCGA and local cohorts." (PMID 34604079, 2021). "Expression of BGN, SPP1, LINC01415, and LINC01614 was much higher in tumor samples than in normal esophageal tissues." (PMID 33362844, 2020). "In addition to the findings presented in this study, recent research has further explored the role of LINC01614 in various tumour types." (PMID 40735832, 2025). "These significant differences encouraged our speculation that LINC01614 might be a tumor staging or progression influential factor, and a high level of LINC01614 might lead to an advanced tumor stage." (PMID 38655053, 2024). "Altogether, these findings demonstrated that LINC01614 can promote tumor growth in vivo." (PMID 39596660, 2024). "In addition, we used zebrafish tumor models to study tumor growth and metastasis, particularly to decipher the initial steps of the metastatic cascade regulated by exosome-packaged LINC01614." (PMID 36209111, 2022). "In addition, the levels of LINC01614 in primary CAFs positively associated with the mRNA levels of SLC38A2 and SLC7A5 in the paired LUAD tumor cells." (PMID 36209111, 2022). "High LINC01614 expression was correlated with tumor size, histological grading, and staging." (PMID 36209111, 2022). "Similarly, we found that LINC01614 knockdown significantly reduced CRC tumor weight." (PMID 39282156, 2023). "By sequestering miR‐128, LINC01614 can effectively derepress the expression of miR‐128 target genes, leading to the dysregulation of the RAS/MAPK signalling pathway and promoting tumour progression." (PMID 40735832, 2025). "This was supported by a previous study that LINC01614 also played a crucial role in the PI3K-Akt signaling pathway, ECM receptor interaction, and promoted tumor progression." (PMID 38655053, 2024). "LINC00702, AC121247.2, HSD11B1-AS1, NR4A1AS, AC011472.4, LIPE-AS1, etc., were lower expressed in tumor tissues, conversely, AP001434.1, LINC02257, LINC01655, LINC01614, AF015262.1, LMNTD2-AS1, etc., were highly expressed in tumor tissues." (PMID 34671639, 2021). "AC093642.1, AC243829.4, AL121748.1, LINC01614, and LINC02728 were expressed at higher levels in the higher neoplasm histological grade group." (PMID 35047016, 2021).
tumor (continued). "High expression of SPP1, BGN, LINC01614, and LINC01415 in tumor samples was validated further by RT-qPCR." (PMID 33362844, 2020). "LINC01614 and FOXP1 were found to be up‐regulated in LUAD tumours and cells, whereas miR‐217 was down‐regulated." (PMID 29934982, 2018). "We found that the expression of LINC0711, LINC01094 and LINC01614 failed to exhibit an apparent difference between GC samples and non-tumor samples." (PMID 36249015, 2022).